GPT (glutamic--pyruvic transaminase)
Diseases named in the same sentence as GPT in open-access papers (continued):
Sharing a sentence is not in itself a finding about the gene and the disease.
Obesity (continued). "White and red blood cell count, thrombocyte, sodium, glucose, insulin, HbA1c, uric acid, triglyceride, LDL-cholesterol, ASAT/GOT, ALAT/GPT, GGT, alkaline phosphatase, ferritin and CRP values were significantly higher in patients with obesity compared to controls with a normal BMI." (PMID 40463745, 2025). "In this study, by analyzing three GEO datasets and verifying in 24 patients, we identified that CCRL2, GPT, LGALS12, PC, SLC27A2, SLC4A4, and TTC36 might be the key genes that play an important role in obesity pathogenesis." (PMID 36313453, 2022). "Therefore, there has been increasing interest in identifying bioactive compounds that have potential for reducing triglyceride, non-HDL cholesterol, GPT and GOT and also enhancing adiponectin levels to help manage obesity and its associated metabolic diseases." (PMID 33440605, 2021). "In our study, the serum levels of the liver function marker ASAT/GOT were not significantly elevated in female patients with obesity compered to controls, while ALAT/GPT, GGT, and alkaline phosphatase (ALP) were all found to be significantly elevated." (PMID 39081789, 2024).
Cirrhosis (831 papers, 1996 to 2026). A chronic disorder of the liver in which liver tissue becomes scarred and is partially replaced by regenerative nodules and fibrotic tissue resulting in loss of liver function. "In a preliminary study, DMN induced LC, by increasing GOT, GPT, total cholesterol, and ALP levels and by reducing final body weight, total protein, albumin, and liver weight; however, ISN protected the liver from cirrhosis and improved liver function compared to LC rats." (PMID 36559177, 2022).
Hepatitis (806 papers, 2004 to 2026). Inflammation of the liver. "Patients with CMV/EBV (85.7%) and acute HIV infection (50%) had a significantly higher incidence of hepatitis (glutamic pyruvic transaminase [GPT] > 2 times the upper limit of the normal range)." (PMID 40142520, 2025). "The proposed system utilizes SAX to extract patterns of glutamic pyruvic transaminase (GPT) from data obtained from patients with hepatitis." (PMID 35890775, 2022). "Plasma GOT and GPT are enzymes recognized as indicators of hepatitis, liver cirrhosis, and cardiac infarction." (PMID 29607219, 2018). "Rising GPT and GOT levels are an index for the diagnosis of liver damage with hepatitis or hepatic toxicity." (PMID 36364646, 2022). "Glutamic oxaloacetic transaminase (AST) and glutamic pyruvic transaminase (ALT) levels indicate liver injury, and a high AST/ALT ratio may lead to liver cirrhosis, hepatitis, and liver cancer." (PMID 38420580, 2024). "Serum liver enzymes (GOT, GPT) and total serum bilirubin were all significantly (p < 0.001) more often elevated in hepatitis A than in non-A patients." (PMID 34221712, 2021).
Insulin resistance (732 papers, 2007 to 2026). Increased resistance towards insulin, that is, diminished effectiveness of insulin in reducing blood glucose levels. "These previous reports provided evidence that an elevated ALT (GPT) is significantly associated with insulin resistance and a decline in β-cell function, which was different to our findings." (PMID 34442147, 2021). "Supplementation with this oil prevented liver steatosis and insulin resistance in rats and promoted reductions in GOT and GPT, as well as an improvement to the liver damage caused by alcohol, indicating a protective effect against liver damage caused by chronic ethanol." (PMID 35956414, 2022). "Up-regulates insulin and leptin levels to down-regulate body weight, fat, GLU, Insulin resistance, GOT, GPT." (PMID 35548468, 2022). "ALω-3 supplementation increased serum Trolox equivalent capacity, significantly reduced serum GPT levels (p < 0.01), and enhanced postprandial glucose tolerance (p < 0.001), although it did not alter insulin resistance (HOMA-IR)." (PMID 40722894, 2025). "Several cross-sectional studies and observational cohort studies reported positive correlations between elevated ALT (GPT) and both systemic and hepatic insulin resistance, and that this could predict the development of type 2 diabetes." (PMID 34442147, 2021).
metabolic syndrome (688 papers, 2007 to 2026). A cluster of metabolic risk factors for CARDIOVASCULAR DISEASES and TYPE 2 DIABETES MELLITUS. "Another related consequence of the metabolic syndrome is the increment of the he-patic enzymes alanine transaminase (GPT) and aspartate transaminase (GOT) in plasma." (PMID 36364861, 2022). "Importantly, these dietary conditions did not induce hepatic damage, as evidenced by unchanged liver enzyme levels (GOT and GPT), corroborating previous findings on EVOO’s protective effects against dyslipidemia." (PMID 40362302, 2025). "The significant association with GPT and not with GOT may be explained by the greater sensitivity of GPT for metabolic syndrome, which also affects 8-OHdG." (PMID 32660613, 2020).
COVID-19 (641 papers, 2020 to 2026). A disease caused by infection with severe acute respiratory syndrome coronavirus 2. "There was a slight but significant elevation of glutamic oxaloacetic transaminase (GOT) and glutamic pyruvic transaminase (GPT) in the COVID-19 group compared to non-COVID-19 patients (p < 0.01 and 0.03, respectively)." (PMID 37386635, 2023). "In contrast, neonatal GOT and GPT levels were slightly higher among those born to women who required hospitalization for COVID-19." (PMID 37628369, 2023). "The latest studies on SARS-CoV-2 have indicated that the incidence of liver injury in patients with COVID-19 ranges from 14.8 to 53%, manifesting as abnormal glutamic-pyruvic transaminase (ALT), glutamic-oxalacetic transaminase (AST) and bilirubin levels." (PMID 34646834, 2021). "Laboratory findings like chest X-ray, ESR, white blood cell (WBC) count, lymphocyte count, C-reactive protein (CRP), serum glutamic pyruvic transaminase (SGPT), serum ferritin, PT, D-dimer, and serum creatinine are important markers for the diagnosis and prognosis of COVID-19 illness (p < 0.05)." (PMID 34490284, 2021). "In this regard, the correlation found between viral RNA load in plasma and higher levels of LDH and GPT could suggest a direct or indirect role of viral replication in mediating tissue destruction in COVID-19." (PMID 33317616, 2020). "Creatinine, GPT, ALP, and GOT values were shown to be higher than the normal range in some COVID-19-infected patients." (PMID 34703628, 2021). "Other predictors of COVID-19 mortality include albumin, total bilirubin, Serum Glutamic Oxaloacetic Transaminase (SGOT), Serum Glutamic Pyruvic Transaminase (SGPT), nitrogen urea (p-ES), C-reactive protein (CRP), lactate dehydrogenase (LDH) and ferritin levels." (PMID 38216918, 2024). "Furthermore, six core gene targets including CAT, NOS2, CXCR3, MAPK1, GPT, and ICAM1 of VA against CHOL/COVID-19 were identified using Cytoscape tool." (PMID 34176789, 2021).
Thrombocytopenia (633 papers, 1983 to 2026). A reduction in the number of circulating thrombocytes. "Conversely, elevated levels of LDH, AKP, GPT, prolonged PT, abnormal leukocyte count, and thrombocytopenia were associated with a poor prognosis." (PMID 40990007, 2024). "Important laboratory findings include high erythrocyte sedimentation rate (156; 22.6%), raised serum glutamic pyruvic transaminase (73; 10.5%), random blood sugar (54; 7.8%), leukopenia (72; 10.4%), thrombocytopenia (41; 5.9%), and others." (PMID 30526743, 2019). "Laboratory investigation revealed thrombocytopenia and increased levels of serum total bilirubin, direct bilirubin, creatine, urea, alanine aminotransferase/serum glutamic pyruvic transaminase, aspartate aminotransferase/serum glutamic oxaloacetic transaminase, and creatine phosphokinase." (PMID 35363190, 2022). "Splenectomy was inversely associated with thrombocytopenia and ALT/GPT increase." (PMID 34593940, 2021). "Patients with thrombocytopenia, elevated GOT, GPT, β2-microglobulin, and high maximal SUVt also had poorer OS, but the results were not statistically significant." (PMID 29137104, 2017). "It should be performed if the patient experiences symptoms such as bone pain, sternum tenderness, fever of unknown origin, anemia, leukopenia, thrombocytopenia, or laboratory tests that show elevated levels of LDH, AKP, GOT, and GPT." (PMID 40990007, 2024).
liver dysfunction (628 papers, 2002 to 2026). "A damaged liver often leads to the release of liver enzymes such as GOT and GPT, which is a crucial indicator of liver dysfunction." (PMID 39851554, 2025). "The levels of serum GOT and GPT are two important indicators of liver function, and the abnormally high levels are generally tested as predictors of liver dysfunction." (PMID 34944214, 2021). "In this study, diazinon administration caused liver dysfunction and significant increases in serum GOT and GPT levels compared to the control group (Figure." (PMID 29062807, 2017). "Malaria associated liver dysfunction is usually characterized by a rise in serum bilirubin along with the rise in serum GOT and GPT levels from mild abnormality to more than three times the upper limit of normal." (PMID 25886020, 2015). "Plasma GOT and GPT, indicators of hepatopathy, were significantly higher for the HF group than for the LF group." (PMID 21799697, 2011). "Additionally, the levels of GOT and GPT (biochemical markers of liver dysfunction) decreased in a dose-dependent manner in the NV groups compared with those in the HFD group." (PMID 36101393, 2022). "Lactate metabolism and albumin levels may influence serum LDH and GA levels due to liver dysfunction; thus, we analyzed serum GPT levels to verify the measurements for all the patients who did not have liver dysfunction." (PMID 36589820, 2022). "Therefore, it can be confirmed by accumulated studies that the increase in GOT and GPT levels is directly related to liver dysfunction and tissue damage." (PMID 35620406, 2022). "Alcohol administration significantly increased the activities of glutamic oxaloacetic transaminase (GOT), glutamic pyruvic transaminase (GPT) in serum, and the levels of triglyceride and lipid peroxide in the liver, suggesting acute alcohol-induced hepatopathy." (PMID 23213269, 2012). "Furthermore, measurements of plasma GOT and GPT clarified that AP suppressed fatty liver-induced hepatopathy." (PMID 21799697, 2011). "Additionally, the levels of GOT and GPT, which are well-known biomarkers of hepatocyte damage, were approximately three to four times higher in the R-Ich group than the Con group, which provides clear evidence of liver dysfunction and damage." (PMID 34305907, 2021). "In summary seven patients developed hepatopathy between 0.2 and 31.3 (mean 6.3, median 0.7) years of age, defined as elevated liver enzymes (GOT, GPT, GGT) and sonographic findings." (PMID 33446227, 2021). "Liver dysfunction was assessed on the basis of enzymatic activities of circulating liver enzymes glutamate oxaloacetate transaminase/aspartate glutaminase (GOT/AST) and glutamate pyruvate transaminase/alanine aminotransferase (GPT/ALT)." (PMID 33362762, 2020). "Kidney disorder could be seen from the increase of blood urea nitrogen (BUN) and creatinine, while liver dysfunction could be seen from the increase of serum glutamic-oxaloacetic transaminase (SGOT) and serum glutamic-pyruvic transaminase (SGPT) activities." (PMID 32399477, 2020).
anemia (623 papers, 2003 to 2026). A reduction in the number of red blood cells, the amount of hemoglobin, and/or the volume of packed red blood cells. "Blood examination revealed a slight elevation of C-reactive protein (CRP), glutamate oxalate transaminase (GOT), glutamate pyruvate transaminase (GPT), and lactate dehydrogenase (LDH), marked leukocytosis and mild anemia." (PMID 39781309, 2024). "Grade 2 and 3 anemia was observed in 11.6% and 3.1% of the patients, respectively, whereas <2.7% exhibited a significant increase in bilirubin, GOT, and GPT levels." (PMID 33777520, 2021).
fibrosis (402 papers, 2006 to 2026). the formation of excess fibrous connective tissue in an organ or tissue in a reparative or reactive process. "WC: waist circumference; SGOT: serum glutamic-oxaloacetic transaminase; SGPT: serum glutamic pyruvic transaminase; CAP: controlled attenuation parameter; dB/m: decibels per meter; FS: Fibrosis score kilopascals (kPa), SD: standard deviation." (PMID 39238753, 2024).
type 2 diabetes (370 papers, 2008 to 2026). "Six out of twenty selected genes with largest expression difference (CYP1B1, GPT), genes linked to PCOS (RAB5B) or type 2 diabetes (PPARG, SVEP1), and methylation (DMAP1) were replicated in a separate case-control study." (PMID 26975253, 2016). "Some studies have reported that elevated GPT/ALT levels, even within the normal range, predict the development of type 2 diabetes mellitus (T2DM) and metS." (PMID 40271225, 2025).
neutropenia (346 papers, 2005 to 2026). A decrease in the number of neutrophils found in the blood. "Common adverse events seen in the nedaplatin group were increased glutamic-pyruvic transaminase levels, increased creatinine levels and neutropenia." (PMID 34833470, 2021).
non-alcoholic fatty liver disease (346 papers, 2007 to 2026). "This study aimed to evaluate the predictive utility of serum aminotransferases (GOT and GPT) for non-alcoholic fatty liver disease in the context of metabolic risk factors, with an emphasis on early identification before irreversible liver damage occurs." (PMID 40507868, 2025).
liver cirrhosis (326 papers, 2006 to 2026). "HBsAg-positive people showed high values from two liver function tests, including glutamic-oxaloacetic transaminase and glutamic-pyruvic transaminase, and the prevalence rates of liver cirrhosis and liver cancer were also significantly high." (PMID 27048173, 2015). "No obvious correlations with gender, HBsAg, liver cirrhosis, serum albumin, total bilirubin (TBil), glutamic-pyruvic transaminase (ALT), or glutamic-oxaloacetic transaminase (AST) were observed (P > 0.05)." (PMID 31632844, 2019). "Finally, due to the nature of cross-sectional studies, the temporal relationship between HO-1 induction (represented as the (GT)n genotype) and liver cirrhosis, as well as GOT/GPT and AFP, is not clarified in this study." (PMID 33916685, 2021).
Sepsis (280 papers, 2006 to 2026). Sepsis is defined as life-threatening organ dysfunction caused by a dysregulated host response to infection. "Liver function was assessed by determining the activity of serum glutamic-oxaloacetic transaminase (SGOT) and serum glutamic pyruvic transaminase (SGPT) in ononin-treated sepsis rats." (PMID 41221897, 2025). "In hepatocytes, organelle membrane damage causes swelling, hepatocyte necrosis, and the release of cytosolic glutamic oxaloacetic transaminase (GOT) and glutamic pyruvic transaminase (GPT) enzymes, which precede mortality from sepsis." (PMID 31835381, 2019). "The activity level of the pig, microbiological counts of MRSA, and sepsis-associated biochemical parameters (UA, BUN, CRE, GOT, and GPT) were assessed." (PMID 31835381, 2019). "Results showed GOT and GPT levels increased during sepsis, and levels were restored following the administration of human recombinant Hsp72 (rhHsp72)." (PMID 26221596, 2015). "Blood biochemistry values related to inflammation reactions indicated GOT, GPT, C-RP, and NOconcentrations of groups with added wild bitter gourd were all lower than those of the sepsis group." (PMID 25153878, 2014). "Blood biochemistry values related to inflammation reactions indicated GOT, GPT, C-RP, and NO concentrations of groups with wild bitter gourd added all lower than that of the sepsis group." (PMID 25520930, 2014). "The sepsis-induced increases in GOT/GPT activities returned to the control level following rhHsp72 administration (comparison between empty and shaded columns), demonstrating that rhHsp72 ameliorates liver function during sepsis progression." (PMID 26221596, 2015). "The significance was that the increase in PCT levels was much higher than that associated with sepsis, and levels were increased regardless of liver enzyme levels (GPT, 16 IU/L in case 1 vs 1473 IU/L in case 2) and blood acetaminophen level (<5.0 μg/mL in case 1 vs 116.9 μg/mL in case 2)." (PMID 32049787, 2020). "Anti-PD-L1 antibodies have shown significant improvement in liver injury morphology in CLP mice by reducing glutamic pyruvic transaminase (ALT) and glutamic oxaloacetic transaminase (AST) release, as well as decreasing TNF-α, interleukin (IL)-6, and IL-10 mRNA levels in the liver after sepsis." (PMID 38193090, 2023).
Hyperglycemia (240 papers, 2008 to 2026). An increased concentration of glucose in the blood. "Assessing different serum parameters, CAF diet caused hyperglycemia and affected serum lipid profile as well as GOT, GPT and GGT compared to a standard diet." (PMID 34681831, 2021). "Following CSD, the impairment of liver and metabolic functions was clearly demonstrated by the enhanced GOT, GPT, and ALP levels together with the incidences of hyperglycemia, hypertriglyceridemia, hyperlipidemia, and hyperinsulinemia." (PMID 35540828, 2018).
liver failure (233 papers, 2006 to 2026). A liver disease characterized by the liver losing or has lost all of its function. "Only the mouse lines 45-2 and 50-4 revealed significant liver failure reflected by enhanced serum glutamic-pyruvic transaminase (SGPT) levels." (PMID 23233866, 2012). "Cardenas and Gines showed that the combined significant elevations in plasma GPT, GOT, and creatinine levels might be linked with hepatic failure." (PMID 39801977, 2025). "GPT and GOT in serum are markers of hepatic damage, and the GPT and GOT levels in serum were increased in liver failure patients." (PMID 34276667, 2021).
Hypoalbuminemia (227 papers, 2005 to 2026). The concentration of albumin in the blood circulation is below the lower limit of normal. "At the same time, elevated levels of lactate dehydrogenase (LDH), glutamic-pyruvic transaminase (GPT), and glutamic oxaloacetic transaminase (GOT), as well as hypoalbuminemia, were detected in 82.9%, 34.1%, 61.0%, and 58.5% of patients, respectively." (PMID 40990007, 2024).
Hyperbilirubinemia (216 papers, 2008 to 2026). An increased amount of bilirubin in the blood. "In addition, the liver marker enzyme, including GPT, GOT, ALP and MDA level has been shown to increase under conditions of hepatotoxicity, which may be followed by hyperbilirubinemia in severe cases." (PMID 26153201, 2015).
hyperlipidemia (213 papers, 2011 to 2026). "On day 4, his biochemical parameters revealed transaminitis SGOT (serum glutamic-oxaloacetic transaminase) 622 U/l, SGPT (Serum Glutamic Pyruvic Transaminase) 396 U/l, and hyperlipidemia 489 U/l, and RFT was normal and diagnosed as acute pancreatitis." (PMID 39664920, 2024). "Although no morphological or histological changes were observed in the livers of PHL rats, GOT and GPT levels were significantly higher than in CON rats, owing to the induction of hyperlipidemia." (PMID 37765165, 2023).